IL18 (interleukin 18)
Diseases named in the same sentence as IL18 in open-access papers (continued):
Sharing a sentence is not in itself a finding about the gene and the disease.
diabetes (continued). "Estudos evidenciam que o aumento da IL-18 no soro está associado também a alguns fatores de risco, como diabetes melito (DM) tipo 2 e síndrome metabólica, além da gravidade da aterosclerose." (PMID 32491018, 2020). "In this study, we demonstrate that acute melioidosis patients rely on NK cells for survival and excessive levels of pro‐inflammatory cytokines IL‐15 and biologically inactive IL‐18 contribute to poor outcome independent of diabetes comorbidity." (PMID 31032897, 2019). "With diabetes, NLRP3 is stimulated by the ER stress and cleaves and stimulates caspase-1, leading to secretion and release of the pro-inflammatory cytokines IL-1β and IL-18." (PMID 30657794, 2019). "Our results showed a significant association between the IL-18 -607 polymorphism and RCC, particularly in people without smoking or alcohol drinking behavior, and those without diabetes." (PMID 30925760, 2019). "But, other risk factors such as gender, smoking or addiction, hyperlipidemia and diabetes, did not influence blood levels of IL-18, MPO and MMP-9." (PMID 31516856, 2019). "While the deleterious role of IL-1β in renal cells during diabetes is not clearly established, IL-18 deleterious role is clearly demonstrated." (PMID 29359167, 2017). "Of note, the important NK cell activation factor IL-18 is not required for diabetes as MyD88 signaling is necessary to process functional IL-18." (PMID 22558306, 2012). "Notably, IL-18R1 is the receptor of proinflammatory cytokine IL-18, and overproduction of IL-18 has been noted as a proxy biomarker for overall inflammation and immune activation in HIV infection and metabolic-inflammatory diseases (e.g., diabetes and non-alcoholic fatty liver diseases (NAFLD))." (PMID 38643166, 2024). "In diabetes, excessive FTO downregulates TNIP1, a central regulator of inflammation, thereby activating NF-κB and subsequently increasing inflammatory cytokines (IL-1β and IL-18) in an m6A-dependent manner, ultimately leading to vascular endothelial dysfunction." (PMID 37781923, 2023). "The retinal expression level of Il18 was not affected by diabetes in both WT and Il33−/− mice." (PMID 37671525, 2023). "Additionally, PCB118 increased the production of inflammatory factors (IL-6, IL-18, and CCL-2) that may damage islet cells, possibly leading to the occurrence and development of diabetes." (PMID 34055976, 2021). "Activation of the diabetes-mediated pyroptosis-related inflammasomes, such as nucleotide-binding oligomerization domain-like receptor protein 3 (NLRP3), Toll-like receptor 4 (TLR4), caspase-1, interleukin (IL)-1β, and the IL-18 axis, plays an essential role in DKD lesions." (PMID 33692782, 2021). "Together, our findings show a regulatory role of AIM2, mediated by IL-18, in shaping gut microbiota and reducing bacterial translocation and proinflammatory response against insulin-producing β cells, which ultimately results in protection against T1D onset in an STZ-induced diabetes model." (PMID 32295112, 2020). "The adjusted ORs for carriers with genotypes AC and CC at IL-18 -607 were 0.44 and 0.35 among subjects without diabetes (95% CI = 0.28–0.81 and 0.21–0.68, respectively) and 0.38 and 0.36 among those with diabetes (95% CI = 0.18–1.02 and 0.13–1.58, respectively), respectively." (PMID 30925760, 2019). "Stratifying the population according to smoking, alcohol drinking, hypertension, and diabetes status revealed a different distribution of IL-18 -607 genotypes among non-smokers, non-drinkers, and patients without diabetes, but not among smokers, drinkers, or patients with diabetes." (PMID 30925760, 2019). "In prediabetes and diabetes conditions, circulating levels of IL1β, IL18, and IL1RA, which are induced by IL1β, are elevated, and treatment with IL1β induces insulin resistance in adipocytes, implying that IL1β and IL18 have a crucial role in the development of type 2 diabetes." (PMID 27229537, 2016).
diabetes (continued). "IL-18 exhibited yet a different pattern, in that its expression was not influenced by diabetes but was inhibited by the ketogenic diet, which could thereby produce some protective effect directly." (PMID 21533091, 2011). "Similarly, renal gene expression of Il1β, Il18 and Ccl2 as well as glomerular accumulation of CD68-positive cells, which is a macrophage marker, were increased in the MCC950-treated diabetic animals, consistent with MCC950 promoting renal inflammation in diabetes." (PMID 35048962, 2022). "In people without diabetes SRA1 expression was associated with CCL3 (r = 0.298, p = 0.036), CCL8 (r = 0.344, p = 0.021), CXCL11 (r = 0.400, p = 0.003), TNF-α (r = 0.317, p = 0.030), TGF-β (r = 0.514, p < 0.0001), IL13 (r = 0.310, p = 0.028), and IL18 (r = 0.547, p < 0.0001)." (PMID 34685582, 2021). "Nine biomarkers were positively associated with depressive symptoms in the total sample (CCL11/eotaxin, CCL25, CDCP1, FGF-21, IL-8, IL-10RB, IL-18, MMP-10, TNFRSF9; all p < 0.05) without interaction by diabetes type." (PMID 39799156, 2025). "As expected, this study demonstrates significantly increased IL-6, IL-8, IL-18, and MCP-1 expression in patients with diabetes, with and without VCs, compared to the control group." (PMID 39519313, 2024). "Our current report also showed a step ladder increase of IL-18 in severe DENV infection without and with comorbidity (hypertension and or diabetes) to the mild one." (PMID 34840991, 2021). "In contrast, cells infected with diabetes-related EV strains secreted enhanced levels of IL8, IL18, and MCP1, but not of IL6." (PMID 32664675, 2020). "The aim of this study was to investigate whether and how IL-18 concentration in serum is prospectively associated with cardiovascular deaths in the 2-year follow-up in patients with various stages of CKD and the history of AMI in the previous year, but without diabetes mellitus." (PMID 26669254, 2015). "In patients with DKD, serum IL-18 and TNF-α levels were higher in patients with diabetes than nondiabetic controls." (PMID 26064987, 2015). "Besides, TGF-β and IL18 independently predicted the SRA1 expression in non-diabetics as well as in the total (diabetic and non-diabetic) study population, while TNF-α and IL-2RA were the independent predictors of SRA1 only in people with diabetes." (PMID 34685582, 2021).
viral infection (176 papers, 2007 to 2026). "In fact, the role of IL-18, a pro-inflammatory cytokine associated with the Th1 immune response, has been implicated in various viral infections." (PMID 41227147, 2025). "The consequent decline in the release of IL-1β and IL-18 leads to a reduction in inflammation caused by viral infection." (PMID 40189592, 2025). "Markedly elevated serum IL-18 levels are associated with severe disease and mortality in some viral infections characterized by cytokine storms." (PMID 40507498, 2025). "Consistent with the previous observation that the bronchial epithelium is an important source of IL-18 following viral infection, we found IL-18 staining associated with bronchial epithelial cells." (PMID 28830544, 2017). "Although bacterial infections are commonly characterized by the induction of IL-6 and CRP, viral infections are generally associated with marked elevation in plasma IL-18 and ferritin with concomitant low circulating CRP levels." (PMID 27977798, 2016). "IL-18 has been extensively studied and is known to be involved in responses to viral infections, hepatocyte apoptosis, and linked to chronic liver damage." (PMID 25166593, 2014). "Soluble CD14 (sCD14) and IL-18 are two biomarkers of innate immune activation associated with viral disease." (PMID 25166593, 2014). "Increased levels of IL-18 and its binding protein have been linked to the severity and progression of infectious diseases such as malaria while IL-1β and IL-6 are associated with sepsis and viral infections like COVID-19." (PMID 38251210, 2024). "In vivo, we demonstrated that IL18-hUCMSC infusion could reduce the body weight loss caused by a viral infection and significantly improve the survival rate." (PMID 36707501, 2023). "Furthermore, IL-18 is also associated with worsening and mortality in other viral diseases such as influenza and dengue." (PMID 36111789, 2022). "Interestingly, basal levels of IL-18 and IL-22 were higher in Viperin−/− animals than WT animals before virus infection, suggesting a potential predisposition of these mice for INFγ-Th1 stimulation." (PMID 30665948, 2019). "However, little is known concerning the relation between high level of IL-18 associated with the viral infection and intestinal permeability." (PMID 29601578, 2018). "Based on our results, we hypothesize that TLR3 might be activated by a viral infection, which then induces miR-134 up-regulation and causes increased circulation of IL-18 in AOSD." (PMID 28646209, 2017). "Specifically, IL-18 is increased in viral infections and plays a central role in viral clearance by activating CD8+ T cells." (PMID 41601646, 2026). "Extracellular cleavage of IL-36 cytokines can be advantageous over intracellular processed IL-1β and IL-18 in response to viral infection." (PMID 40121229, 2025). "MAIT cells serve as the primary source of IFN-γ production in response to IL-12 and IL-18 stimulation, and their reduction has been observed in various viral infections." (PMID 40510360, 2025). "When mice were given MCC950 after viral infection, the levels of IL-1β and IL-18 in their bronchoalveolar lavage fluid were significantly reduced." (PMID 40906404, 2025). "ST3GAL2 resists viral infection by downregulating pro-inflammatory cytokines (IL-6, IL-18, IL-1β, IFN-β, TNF-α) and upregulating anti-inflammatory cytokines (IL-4, IL-10, IL-13)." (PMID 40755778, 2025). "Macrophages produce IL-18 at the very early stages of viral infection and induce the production of IL-6 and IFN-γ." (PMID 39273479, 2024). "IL-18 plays a role in maintaining the Th1 inflammatory response to viral infection, and it induces the downstream production of IFNG." (PMID 38540716, 2024). "IL-18 contributes to the immune response against viral infections by activating T cells and natural killer (NK) cells, promoting their cytotoxic activity." (PMID 38251210, 2024).
viral infection (continued). "The literature data indicate that IL-18 strategically generates the immune response against viral infections and is usually proinflammatory." (PMID 39273479, 2024). "In the early stage of a viral infection, IL-1β and IL-18 promote the activity of CD8+ T cells and induce antibody secretion, thus playing protective roles; however, when overproduced, these cytokines destroy benign tissues." (PMID 39203394, 2024). "This is the case during viral infections as well as some bacterial infections in which cytokines such as IL-18, IL-12, and type I IFNs are sufficient to stimulate MAIT cells." (PMID 39128630, 2024). "It is now clear that NK cells remember previous activation events with distinct forms of innate memory and memory-like responses following hapten exposure, viral infection, and combined activation with IL-12, IL-15, and IL-18." (PMID 40729303, 2024). "Reduced production of the pro-inflammatory cytokine IL-18, in turn, can lead to uncontrolled bacterial and viral infections of the oral cavity." (PMID 38915777, 2024). "In patients with viral infections, high levels of IL‐18 free have been recognized suggesting the important role of IL‐18 in the cytokine storm, along with IL‐1β and IL‐6, as in the case of COVID‐19." (PMID 36385417, 2023). "Ferritin is mainly produced in the liver and stimulated by interleukin -18 (IL-18) released from monocytes because of viral infection." (PMID 37567939, 2023). "Subsequent work has now shown that MAIT cells require IL-12 and IL-18 stimulation to respond to viral infections." (PMID 38003807, 2023). "Cell-mediated immune responses are important in the protection of viral infections, and, therefore, it seemed logical to investigate the efficacy of IL-18 as a vaccine adjuvant against IBDV." (PMID 38006048, 2023). "For instance, viral infections (dengue, hepatitis C, and influenza viruses) trigger activation by IL-18 release in combination with IL-12 and IL-15 and/or IFN-α/β." (PMID 38003807, 2023). "In particular, in viral diseases the imbalance of the IL18/IL-18BP ratio appears particularly significant for the pathophysiology of the abnormal response to the infection." (PMID 36385417, 2023). "A possible classification of the main patterns of cytokines inflammatory mechanisms is based on the axes IL-6/CRP and IL18/Ferritin as infection programs related to bacterial and viral infections." (PMID 36385417, 2023). "MAIT cells aid in host defense in an antigen-independent manner, as they respond to a variety of cytokines such as IL-12 and IL-18 during viral infections." (PMID 37163092, 2023). "Both in vivo and in vitro experimental data demonstrated that viral infection induces innate immunity, with mRNA expression levels of two key inflammatory factors, interleukin-1β (IL-1β) and IL-18, significantly upregulated." (PMID 37063902, 2023). "This release of LDH can act as a danger signal, alerting the immune system to the presence of the infection and triggering a response by production of cytokines such as IL-1 and IL-18, which can help to activate immune cells and fight off viral infections." (PMID 37046952, 2023). "The cytokines IL-12 and IL-18, common signals from viral infection, activate MAIT cells in an MR1-independent manner, associating an innate-like activation mode to MAIT cells." (PMID 38003807, 2023). "IL‐18 plasma levels are commonly elevated in viral infections, exceeding 1,000 pg/ml during the acute phase of Epstein–Barr virus (EBV) and in human immunodeficiency virus (HIV) infection, particularly in patients with severe cases." (PMID 36707501, 2023). "Pathway enrichment analysis revealed activated IFN-γ, IL-1, and IL-18, autophagy, and viral infection response." (PMID 36203777, 2022). "In mouse model infected with Herpes simplex virus (HSV), IL-18 has a protective role against viral infection." (PMID 36032110, 2022). "For IL-18, the highest concentrations were detected in samples from patients with severe Wuhan strain viral infection." (PMID 36430621, 2022).
viral infection (continued). "On the other hand, mAbs which promoted viral infection of human macrophages enhanced systemic IL-18, IL-1RA, and CXCL10 particularly in early disease." (PMID 35483404, 2022). "In response to viral infection, IL-18 is released, which induces ferritin, thus explaining the frequently observed hyperferritinemia in viral infections, and stimulates natural killer cell‐mediated IFN‐γ production for antiviral innate immune responses." (PMID 35930243, 2022). "The AIM2 gene is related to the hyperinflammatory manifestation of MIS-C patients since triggers caspase-1 and unleashes pro-inflammatory cytokines such as IL-1β and IL-18,19 which are also involved in the innate immune response to viral infections." (PMID 35770252, 2022). "While the axes IL-1β/IL-6 link to CRP production in bacterial infections, IL-18 production links to transferrin in viral infection." (PMID 35663992, 2022). "The combination of IL-18-induced apoptosis and IL-22-induced proliferation results in faster turnover of villi epithelial cells than the rate of viral infection of new cells." (PMID 35216425, 2022). "First, IL-18, a cytokine belonging to the IL-1 family and intervening in cellular immune response it is secreted upon macrophage activation in viral infections and courses with endothelial damage in lung tissue." (PMID 36238287, 2022). "IL-18 is a potent and fundamentally important cytokine in host defence, particularly against viral infections." (PMID 32918930, 2021). "IL-18 BPa is strongly upregulated during inflammation, including malignancies such as cancer but also by some viral infections, with some viruses having evolved the capability to express active viral forms of IL-18 BPa." (PMID 33572894, 2021). "On the contrary, rhLAV-BPIFB4 induced a rapid increase in IL-18 and IL-1b levels, shown largely protective during the early stages of the virus infection." (PMID 34396395, 2021). "Unexpectedly, we found that IL-18 signaling is dispensable during viral infection in vivo, while the upregulation of nutrient transporters is primarily MyD88-dependent." (PMID 34093543, 2021). "Activation of MAIT cells in viral infections is antigen-independent and mediated by the cytokines IL-12 and IL-18, rendering MAIT cells capable of orchestrating inflammation even in the absence of bacterial infection." (PMID 33546489, 2021). "Caspase-1, in turn, cleaves inactive pro-IL-β and pro-IL-18 to yield active IL-1β and IL-18, which activate subsequent systemic immune responses to limit viral infection and spread." (PMID 33652815, 2021). "IL-18 is an important cytokine produced by macrophages in the early stages of viral infections and subsequently stimulates the production of IL-6 and IFN-γ, which are considered essential for optimal viral host defense." (PMID 34073872, 2021). "On the other hand, IL-18 plays a significant role in the skin inflammatory response to viral infection; increased IL-18 in the presence of HPV infection can reduce the cellular immune response." (PMID 34833157, 2021). "More specifically, MIP-1a, IL-18, and RANTES have been associated with viral infection, Alzheimer’s disease, and traumatic brain injury, respectively." (PMID 33622348, 2021). "One of the fundamental innate immune responses to viral infections includes the processing and release of pro-inflammatory cytokines such as interleukin (IL-1β and IL-18) through the activation of inflammasome." (PMID 32210961, 2020). "IL-18 is another member of IL-1 cytokine family and plays a protective role in many virus infections." (PMID 33553280, 2020). "Yet, monocytes/macrophages produce the majority of inflammasome related cytokines (IL-18 and IL-1β) in other viral infections and play crucial roles in preventing the most severe manifestations of HSV infection in mouse models." (PMID 32101570, 2020).